RARB (retinoic acid receptor beta)
Diseases named in the same sentence as RARB in open-access papers (continued):
Sharing a sentence is not in itself a finding about the gene and the disease.
tumor (continued). "In conclusion, the role of RARβ is cell-specific, where this gene acts as a tumour suppressor in A549 parental cells, yet enhances the stemness characteristic of CSCs." (PMID 33995625, 2021). "In many neoplastic diseases, expression of RARβ is often downregulated or lost indicating that RARβ plays an important role in tumour suppression." (PMID 34178631, 2021). "The study showed that inhibition of miR-29b suppressed cell proliferation, growth, migration, invasion, and tumour growth via RARβ." (PMID 33805295, 2021). "The findings showed that RARα, RARβ, RARγ, and RXRγ were present in significantly lower levels in the tumor tissues." (PMID 32012980, 2020). "Down regulation of RARβ combined with AP-1 up-regulation triggers tumour progression and proliferation of NSCLC cells." (PMID 32909215, 2020). "RARβ is a tumor suppressor gene whose expression is significantly decreased in human cancers and increased with atRA treatment." (PMID 32909215, 2020). "From a basic and mechanistic standpoint, another important result of the study regards the specific involvement of RARβ in the anti-tumor action exerted by ATRA in retinoid-sensitive TNBC cells." (PMID 33081033, 2020). "RARβ (Retinoic Acid Receptor Beta) is a putative tumour suppressor gene and a member of nuclear receptor RAR (Retinoic Acid Receptor)." (PMID 30803219, 2019). "Univariate Cox regression tests revealed that low RARβ protein expression (p = 0.001), tumor TNM stage (p = 0.002), distant metastasis (p = 0.001), and differentiation (p = 0.006) were inferior prognostic factors for overall survival." (PMID 30944670, 2019). "Our data indicate that RARβ immunoreactivity was significantly correlated with gender (p = 0.048), tumor differentiation (p = 0.014), and tumor TNM stage (p = 0.036)." (PMID 30944670, 2019). "RARβ has been shown to function as a tumor suppressor, representing an interesting target in cancer research." (PMID 30944670, 2019). "Our group has demonstrated that suppression of RARβ in CAFs via genetic knockdown or with an antagonist named LE135 consistently lowers the chemoresistance of tumor cells that are otherwise promoted by wild-type/untreated CAFs." (PMID 30925918, 2019). "Our findings demonstrated that increased RARβ expression and early tumor stage are independent prognostic biomarkers in patients with CRC." (PMID 30944670, 2019). "In this study, we evaluated the level of RARβ expression in human CRC tissues compared with corresponding tumor-adjacent tissues from the same patients and assessed the relationship between RARβ expression and clinical prognosis." (PMID 30944670, 2019). "RARβ protein expression was significantly lower in CRC samples compared with adjacent matched tumor tissues (χ2 = 18.767, p < 0.001)." (PMID 30944670, 2019). "Taken together, the evidence suggests that RARβ expression is reduced in human tumor cells, likely because of the hypermethylation of its promoter." (PMID 30944670, 2019). "RARB and RASSF1 are important tumor suppressors and loss of expression is associated with a growth advantage and immortalization of tumor cells." (PMID 29851970, 2018). "It was described that cells in which RARβ is deleted or its expression is impaired are selected in the cell population during the phase of rapid tumor growth." (PMID 29301374, 2018). "Among various retinoic acid-responsive genes, RARβ is recognized to act as a tumor suppressor and also have critical roles in the present study for suppressing hepatic carcinogenesis in Lrat KO mice." (PMID 29050312, 2017). "Significantly larger tumour size was noted for cases with RARβ hypermethylation (median 22.3 mm vs 16.5 mm; p = 0.01)." (PMID 28893223, 2017). "In NR genome, promoters of the three tumor suppressors (RARB, CDH1, and EPCAM) were found to be almost exclusively unmethylated by methylation-specific PCR (MSP)." (PMID 28467809, 2017).
tumor (continued). "Previous reports showed that RARβ was frequently epigenetically silenced in tumor progression, which demonstrated that RARβ belongs to a tumor suppressor protein." (PMID 28008143, 2017). "Emerging evidence indicates that Retinoic acid receptor-β (RARβ) is a tumor suppressor in many types of tumor." (PMID 28008143, 2017). "Just similar to other tumor suppressor genes, the CpG islands of RARβ promoter are easily hypermethylated in malignant cells." (PMID 28008143, 2017). "There was enhanced nuclear retinoic acid receptor β (RARβ) visibility within the PSCs in KPC tumours upon treatment with ATRA, which is known to reflect PSC quiescence." (PMID 27061193, 2016). "Multiple studies support that RARβ possesses functional characteristics of a tumor suppressor and indeed, its expression is frequently lost in neoplastic tissues." (PMID 25933005, 2015). "Strong and significant correlation between tumor tissue and autologous controls of RARβ gene promoter hypermethylation prevalence across studies (Correlation coefficient 0.53) was found." (PMID 24796328, 2014). "And we also found significant RARβ gene promoter hypermethylation prevalence correlation between tumor tissue and autologous controls among the included studies (Correlation coefficient 0.53)." (PMID 24796328, 2014). "We also found strong and significant correlation between tumor tissue and autologous controls of RARβ gene promoter hypermethylation prevalence across studies (r = 0.53)." (PMID 24796328, 2014). "HER2 amplification in DCIS tumours was associated with methylation of CDH13 (P = 0.009), and RARβ (P = 0.042)." (PMID 25331261, 2014). "The methylation prevalence was much higher in tumor tissue (meidan methylation prevalence 47.56%) compared to autologous controls (meidan methylation prevalence 17.50%) of RARβ gene." (PMID 24796328, 2014). "In the subgroup analysis, the significant odds of the RARβ promoter methylation in tumor tissue was only changed when comparing to sputum (p = 0.120) and in subjects with Caucasian ethnicity (p = 0.159)." (PMID 24796328, 2014). "This prominent result also give us an understanding that RARB is really an important factor for chemoprevention for tumor progression." (PMID 25197641, 2014). "The consequence of this change is down-regulation of tumor suppressive genes such as RARα, RARβ and CRBP1, and possibly others." (PMID 22920668, 2012). "Analysis of RARβ in either the primary tumour or the metastatic site should be explored in further testing of this combination." (PMID 22134508, 2012). "Patients showing at least one hypermethylated tumor fragment for RARB and/or RASSF1A were considered informative cases for further comparisons." (PMID 18702824, 2008). "This cell cycle block in conjunction with apoptosis and RARβ activation leads to eventual inhibition of PC-3 cell and tumour growth." (PMID 18349838, 2008). "Protein expression of tumour suppressor gene, RARβ was found to be increased in the tumours of the VN/66-1 and combination-treated animals." (PMID 18349838, 2008). "Our findings strongly suggest a potential role of RARβ as a tumor suppressor by mediating the signals of certain chemotherapeutic agents." (PMID 18166136, 2007). "Significant CpG methylation of gene promoters within tumour specimens was found in 28% for p16, 73% for RARβ, 42% for E-cadherin, 65% for cytoglobin and 53% for cyclinA1." (PMID 16449996, 2006). "Significant differences in degree of methylation of individual CpG sites were noted for all genes except RARβ and these differences were in a characteristic pattern that was reproduced between tumour samples." (PMID 16449996, 2006). "In our data, 62% of the normal specimens had MtI>0.05 and this appears to support existing theories that promoter methylation of RARβ is widespread in apparently normal tissues as well as tumour and is, perhaps, an early event in carcinogenesis." (PMID 16449996, 2006).
tumor (continued). "Retinoic acid receptor beta has four alternative splicing forms and the β-2 form appears to possess tumour-antagonizing activity at least in some cancers." (PMID 14970867, 2004). "Retinoic acid receptor beta underwent DNA promoter region methylation in significant percent in several other tumours such as lung, cervical bladder, and prostate." (PMID 14970867, 2004). "In our tumor samples, we determined large amounts of the RARα, RARβ, RXRα and RXRβ transcripts." (PMID 39323992, 2024). "Since it regulates essential pathways associated with the tumor-suppressive effects of retinoids in various epithelial cells, RARβ signaling may play role as a potential tumor suppressor." (PMID 37616260, 2023). "RARβ is necessary to inhibit tumor proliferation and migration." (PMID 36230951, 2022). "Notably, the CRC members identified include the retinoic acid receptor homologs RARA, RARB and the tumour suppressors HIC1 and SMAD3." (PMID 36147741, 2022). "The results revealed the cell specificity role of RARβ, where this gene act asa tumour suppressor gene in A549 parental cells and play the opposite role in A549 CSCs where in CSCs, this gene play role as a tumour promoter." (PMID 33995625, 2021). "This may be explained by the induction of the tumour suppressor effects of ATRA-mediated expression of RARβ in H1299 CisR cells." (PMID 33550205, 2021). "Moreover, inhibitor of growth protein 4 (ING4) was identified as a tumour suppressor that directly interacts with RARβ." (PMID 33805295, 2021). "RARβ, which is the best characterised RA-responsive gene, is widely expressed in epithelial cells, has four alternative splice forms and the beta-2 form appears to possess tumour-antagonising activity." (PMID 33995625, 2021). "Importantly, several enzymes of the vitamin A metabolism and the nuclear receptor RARβ can become potential therapeutic targets in TSC mutant or deregulated neoplasms." (PMID 34178631, 2021). "However, a recent study reported that RARβ acts as a tumour suppressor and as a tumour promoter depending on the splicing variant expressed by the cells." (PMID 33995625, 2021). "More importantly, RARβ is a tumour suppressor and a key target gene of retinoid action." (PMID 33550205, 2021). "Importantly, reactivation of RARβ-dependent signaling that is inhibited by overexpression of GSK-3β returns profoundly unexpected sorafenib treatment outcome (tumor inhibition raised sharply from 48.3% to 93.4%)." (PMID 31938062, 2020). "Tumor-associated GSK-3β is correlated with reduced expression of retinoic acid receptor-β (RARβ), which is caused by GSK-3β-mediated phosphorylation and heterodimerization abrogation of retinoid X receptor (RXRα) with RARα on RARβ promoter." (PMID 31938062, 2020). "Moreover, as RARβ, also RARα was defined as tumor suppressor silenced by extensive cytosine methylation in the promoter responsible of RARα under-expression in MCF-7 cell line, and probably in the dysregulation of ATRA signaling." (PMID 32012980, 2020). "Interestingly, RARβ expression by 9-cis-RA/tideglusib was extensively translocated into cytoplasm, implying that the nuclear export of RARβ is responsible for apoptotic induction and tumor growth inhibition." (PMID 31938062, 2020). "Previous researchers have also reported that RARβ protein is epigenetically silenced with tumor progression, indicating that RARβ might be a tumor-suppressor gene." (PMID 30944670, 2019). "Furthermore, according to the CART results the combination of L1RE1 and RARB was able to separate tumor and benign tissue with a failure rate of 1.4% (91% specificity and 100% sensitivity)." (PMID 29851970, 2018).
tumor (continued). "Higher L1RE1 and low RARB methylation discriminated benign from tumor samples." (PMID 29851970, 2018). "Interestingly, the expression of RARβ is frequently decreased or completely downregulated in primary solid tumors and in their metastasis compared to adjacent non-tumor tissue." (PMID 29301374, 2018). "Retinoic acid receptor beta is a tumor suppressor, and a prognostic indicator in stage I NSCLC." (PMID 27903974, 2017). "Lowered levels of RARB mRNA were observed in 38 (77%) tumor samples." (PMID 27011326, 2016). "RARβ might be an intermediate in a signaling cascade induced by retinoic acid which ultimately activates a tumor-specific apoptosis program mediated by tumor necrosis factor-related apoptosis-inducing ligand." (PMID 25881300, 2015). "Because RARβ acts as a tumor suppressor gene, its reduced expression could lead to enhanced cell proliferation and potentially to tumor formation." (PMID 26462767, 2015). "In conclusion, this meta-analysis showed RARβ promoter methylation was much higher in tumor tissue compared to autologous controls, which indicates promoter hypermethylation of tumor suppressor gene may play an important role in carcinogenesis of the NSCLC." (PMID 24796328, 2014). "Methylation of the retinoic acid receptor β gene, RARB, and that of the checkpoint with forkhead and ring finger gene, CHFR, was associated with tumour stage (RARB: 51·9 per cent for T1–2 versus 33·9 per cent for T3–4, P < 0·001; CHFR: 5·5 per cent for T1–2 versus 12·6 per cent for T3–4, P = 0·005)." (PMID 25052224, 2014). "Recent studies demonstrated that hypermethylation in promoter region of RARβ gene could be found with high prevalence in tumor tissue and autologous controls such as corresponding non-tumor lung tissues (CNTLT), sputum and plasma of the NSCLC patients." (PMID 24796328, 2014). "Many studies have demonstrated that hypermethylation in promoter region of RARβ gene could be found with high prevalence in tumor tissue and autologous controls such as corresponding non-tumor lung tissue, sputum and plasma of the NSCLC patients." (PMID 24796328, 2014). "In the subgroup analysis, the significant odds of the RARβ promoter methylation in tumor tissue was only changed when comparing to sputum (OR = 1.33, 95%CI: 0.98–1.80, P = 0.120) and in subjects with Caucasian ethnicity (OR = 2.38, 95%CI: 0.71–7.92, P = 0.159)." (PMID 24796328, 2014). "In cancer cells with a down-regulated RARβ expression, RA resulted ineffective to reduce cellular migration, suggesting that tumour cells could silence RARβ to facilitate the escape of the tumour triggering the metastatic process." (PMID 24720764, 2014). "The RARβ tumour suppressor gene is the only RAR whose levels decrease drastically in many tumour types, but when RARβ get re-expressed the clinical response might be improved." (PMID 24720764, 2014). "Thus, RARB not only has cell cycle inhibition and tumor suppressant effects, but also anti-inflammatory effects that cease COX-2 related cancerization effects on the oral mucosa." (PMID 25197641, 2014). "Thus, by designing a targeted therapy with RARβ agonists and chromatin remodelling therapeutic agents, the preclinical data suggest that it is conceivable to restore retinoid sensitivity in retinoid-resistant tumours with partial RARβ promoter methylation." (PMID 22134508, 2012). "Taken together, preclinical and clinical data suggest that retinoid-resistant tumours with epigenetic changes at RARβ2 may benefit from a combined therapy with RARβ agonists and chromatin-remodelling drugs such as HDAC inhibitors." (PMID 22134508, 2012). "RARβ may act as a tumor suppressor, and there is evidence that RARβ induction by retinoids is important for inhibiting tumor cell growth." (PMID 22087283, 2011).
tumor (continued). "RARa expression has been demonstrated to be positively linked to proliferative activity and to ER expression, whereas RARb may act as a tumour repressor gene, since its expression is progressively lost with increasing proliferative activity of the tumour." (PMID 22276018, 2009). "The comparative analysis between MSP from washout cells and corresponding primary and/or recurrence tumor sample was done for RARB and RASSF1A genes, including 23 urinary bladder washings and 39 paraffin-embedded UC samples from 20 patients (median age of 68.65, ranging from 42 to 84 years)." (PMID 18702824, 2008). "Twelve patients showed at least one tumor fragment hypermethylated for RARB gene." (PMID 18702824, 2008). "COX-2 expression was not correlated with tumor stages and localisations (data not shown), but was associated with RARα and RARβ mRNA expression in tumor tissue." (PMID 17767717, 2007). "Recent data have also suggested that PPARγ anti-tumor activity required a functional RARβ." (PMID 17767717, 2007). "RARβ has been extensively studied in cancer cells and human carcinomas, and several studies have suggested that it may play a role as a tumor suppressor gene." (PMID 17767717, 2007). "However, we cannot exclude the biological involvement of a very low level of RARβ expression in the human cell lines and tumours." (PMID 15266311, 2004). "Consequently, RARβ was widely regarded as a tumor suppressor in most studies." (PMID 40371351, 2025). "Thereby, it was suggested that EGCG may serve as a potential epigenetic modifier by altering the methylation status of genes encoding retinoic acid receptor beta (RARβ), cadherin 1 (CDH1), and death-associated protein kinase 1 (DAPK1) tumor suppressors to reactivate their expression." (PMID 37446908, 2023). "Indeed, our data suggest that RA-mediated apoptosis in human CRC cells and the significant tumor suppressive effects of RARβ may contribute to the chemopreventive actions of retinoid." (PMID 30944670, 2019). "Our findings indicate that RARβ protein expression is decreased in CRC compared with normal colorectal tissues and is also decreased in tumor tissues compared with corresponding adjacent tissue, indicating that RARβ might have a major role in the suppression of tumor invasion and metastasis." (PMID 30944670, 2019). "In the present study, we investigated the association between RARβ cellular expression and clinicopathological parameters in CRC patients utilizing TMA and appropriate statistical analyses, focusing on the level of RARβ expression in CRC specimens compared with adjacent tumor specimens." (PMID 30944670, 2019). "Our observation in terms of homogeneous and heterogeneous methylation profiles might help to explain why the methylation of APC, RASSF1A, and RARβ genes with a homogeneous pattern have been detected at high frequency and are used successfully in detecting various tumour types as well as MRD." (PMID 30154364, 2018). "To test this hypothesis, we assessed the expression of RARB as well as miR-146a-5p and miR-146b-5p in 48 PTC tumor/normal tissue pairs by Taqman assay to reveal that the expression of RARB was 3.28-fold decreased, and miR-146b-5p was 28.9-fold increased in PTC tumors." (PMID 27011326, 2016). "Consequently, RARβ has been proposed as a tumour suppressor." (PMID 24720764, 2014). "One retinoid receptor, RARβ, has been speculated as a tumor suppressor in several studies." (PMID 18166136, 2007). "RARB (Retinoic Acid Receptor Beta) plays a critical role in cell differentiation and growth inhibition, while CDKN2A (Cyclin-Dependent Kinase Inhibitor 2A) is a tumor suppressor involved in cell cycle regulation." (PMID 39982247, 2025). "Of the six genes, GSTP1, APC, RARB, CCND2, and PTGS2 were tumor suppressors identified as having been hypermethylated in prostate tumor tissues." (PMID 36937425, 2023).